TGFB2 (transforming growth factor beta 2)
Diseases named in the same sentence as TGFB2 in open-access papers (continued):
Sharing a sentence is not in itself a finding about the gene and the disease.
breast cancer (continued). "Thus, to determine whether miR-191:TGFβ2 induced breast cancer migration is SMAD3 dependent, we silenced SMAD3 by using SMAD3-specific siRNA and analyzed the effect on miR-191 induced breast cancer migration." (PMID 25867965, 2015). "Published studies have shown that the roles of transforming growth factor isoforms TGFB1, TGFB2, and TGFB3 in breast cancer prognosis are context-dependent." (PMID 41373732, 2025). "Interestingly, the differentially methylated probe (DMP) for both C1 vs. C3 and C2 vs. C3 contained cg07810039 (TGFB2), whose down-regulation of methylation levels may affect the expression and function of the TGFB2 gene, and consequently the growth and metastasis of breast cancer cells." (PMID 40881682, 2025). "In the bone marrow niche, NG2+/Nestin+ mesenchymal stem cells (MSCs) promote breast cancer DTC dormancy through TGFβ2 and BMP7, and depleting MSCs or the knockout of TGFβ2 in MSCs reactivates dormant cells." (PMID 39682769, 2024). "In conclusion, this study demonstrates that ezetimibe inhibits breast cancer cell migration, invasion, and EMT and identifies TGFβ2's key role in this process." (PMID 38531630, 2024). "Our results show that ezetimibe treatment of breast cancer cells inhibited cell migration, invasion, and EMT, and it significantly suppressed the expression of TGFβ2." (PMID 38531630, 2024). "Then, secreted SRGN binds to CD44 on the breast cancer cell membrane, triggering intracellular signals activating CREB1 that increase the expression of TGFβ2." (PMID 36358747, 2022). "Collectively, BC-derived exosomes and dairy milk-derived exosomes both contain and transfer miR-21, miR-155 and TGFβ2, which may exert synergistic effects in breast cancerogenesis." (PMID 30602375, 2019). "As another illustration of this concept, AKT-mediated phosphorylation of the EMT transcription factor TWIST1 leads to transcriptional activation of the TGFβ2 promoter and activated TGFβ signaling promoting EMT and breast cancer metastasis." (PMID 26204939, 2015). "In conclusion, we show here that downregulation of Dab2, which is commonly observed in breast cancer, can lead to enhanced Ras/MAPK signalling, increased expression of TGFβ2 and constitutive EMT." (PMID 21063401, 2010). "The activities of Itgb1 (coding for integrin β1), TGFβ2 and Vegfα are mediated, at least in part, by Cyr61 (CCN1,)–a secreted matrix protein involved in the clinical progression of breast cancer to an invasive phenotype." (PMID 19450255, 2009). "In cases dependent on TGFB2, increased mRNA expression of TGFB2 alongside higher levels of GDAP1, TBL1XR1, RNFT1, HACL1, SLC27A2, NLE1, or TXNDC16 was correlated with improved OS among breast cancer patients, of which four genes were upregulated in tumor tissues (SLC27A2, TXNDC16, TBL1XR1, GDAP1)." (PMID 41373732, 2025). "Serum levels of EGF, G-CSF, TNFα, Groα, IP10, MIP-1b, MDC, VEGFα, TGFβ1, and TGFβ2 were also high in women with breast cancer compared to the control group (no cancers)." (PMID 38541912, 2024). "TGFB2, and other proteins in this pathway (SRC, AKT, ERK2, and a Slug interactor called LSD1) all maintain the stability of Slug, meaning that Slug levels remain high and drive the aggressive features of this subtype of breast cancer." (PMID 39327614, 2024). "LINC00894 (ENST0000044489) is a non-coding RNA derived from the X chromosome; it regulates the expression of transforming growth factor-beta 2 (TGF-β2) and zinc finger E-box-binding homeobox 1 (ZEB1), which may affect tamoxifen resistance in breast cancer." (PMID 39060766, 2024). "Finally, by comparing the expression patterns of components of the TGF signaling pathway and KDM7A in human breast cancer specimens, we discovered that there was statistically significant correlation between KDM7A and TGFB2/SMAD2/SMAD3/SMAD4." (PMID 34249916, 2021). "There was not any significant relationship between the expression of TGFβ2 expression and the prognosis of breast cancer patients." (PMID 32530106, 2020).
breast cancer (continued). "TGFβ1 and TGFβ2 are potent upstream regulators of Blimp1 in dermal fibroblasts and may potentially act via the c-RAF to AP-1 pathway identified in breast cancer cells." (PMID 28668474, 2017). "Significantly higher scores of positive SRGN and TGFβ2 staining was observed in breast cancer tumors with lymph node metastases (Nodal Positive) compared with breast cancer tumors without lymph node metastases (Nodal Free) (P<0.01)." (PMID 28692037, 2017). "Given that previous studies have shown that increased TGFβ2 expression promotes breast cancer metastasis, we hypothesized that ezetimibe inhibits the migration and invasion of triple‐negative breast cancer cells through TGFβ2." (PMID 38531630, 2024). "We conclude that this SRC-Slug-TGFβ2 axis may contribute to chemotherapy resistance in an aggressive subpopulation of TNBC tumors, and targeting this pathway may help to improve outcomes for this aggressive breast cancer subtype." (PMID 39327614, 2024). "To further validate the association between SRGN and TGFβ2 protein expression in breast cancer patients, we detected the SRGN and TGFβ2 protein expression in 320 non-TNBC tumor tissues (110 Luminal A, 108 Luminal B, and 102 HER2) and 106 TNBC tumor tissues by immunohistochemical staining." (PMID 28692037, 2017). "Among its dysregulated genes, CCND2 is differentially expressed between breast cancer patients with bone metastases and other patients; E2F1 can regulate DZ13 to induce a cytotoxic stress response in tumour cells metastasizing to bone; TGFB2 is related to the bone metastases development." (PMID 25163697, 2014).
pancreatic cancer (48 papers, 2002 to 2026). "It has been reported that high expression of TGFB2 (transforming growth factor-beta 2) in pancreatic cancer is substantially correlated with advanced tumor progression, and high serum levels of TGFB2 in patients are associated with shorter survival." (PMID 38914663, 2024). "Interestingly, our data reveal a positive association between Tgfb2 and Gsdmc in pancreatic cancer, contrasting with the inverse relationship in colorectal cancer." (PMID 39297408, 2024). "In our clinical study, a similar observation was made in the OT-101-treated pancreatic cancer patients versus the low-TGFB2 TCGA population." (PMID 40650134, 2025). "IGF2BP2 binds to METTL14 m6A‐modified TGFB2 mRNA and upregulates TGFB2 expression, resulting in enhanced gemcitabine resistance in pancreatic cancer." (PMID 40448344, 2025). "Trabedersen (AP12009), specific for TGFB2 mRNA, reduced TGFB2 expression in human pancreatic cancer cell lines, resulted in decreased proliferation and migration, and reversed immunosuppressive effects." (PMID 38500662, 2024). "TGFB2 is known to be involved in invasion by pancreatic cancer cells and correlates with patient survival after surgery." (PMID 30279327, 2018). "Likewise, in pancreatic cancer, transforming growth factor-beta 2 (TGF-β2) plays a crucial role in maintaining stemness, chemoresistance, and metastasis." (PMID 41293269, 2025). "A Phase 1/2 trial of the TGFB2-specific antisense oligonucleotide trabedersen in patients with various solid tumors, including colorectal carcinoma, melanoma or pancreatic cancer, has reported that the treatment was safe and well tolerated, though further efficacy studies are pending." (PMID 29369179, 2018). "Similarly, Trabedersen (AP 12009) is a phosphorothioate antisense oligodeoxynucleotide specific for human TGFβ2 mRNA with antitumour activity in human pancreatic cancer, such as reduction in tumour growth, lymph node metastases, and angiogenesis." (PMID 23125850, 2012). "Furthermore, as reported in another study, stabilization of TGFB2 mRNA levels by METTL14-mediated m6A modification and then knockdown of TGFB2 mRNA using shRNA found to lower TGFB2 expression decreased gemcitabine resistance in pancreatic cancer cells and increased cell apoptosis." (PMID 39457004, 2024). "The study suggests that the site of pancreatic tumour growth in vivo strongly influences MUC4 and TGFβ2 expression, tumour morphology, and invasiveness of CD18/HPAF cells." (PMID 14760381, 2004). "Interestingly, the proposed squamous subtype of pancreatic cancer exhibits high expression of FOSL1, TGFB2, SNAI2, and FN1, which is consistent with the FRA1:EMT phenotype we describe here." (PMID 27220889, 2016).
glioblastoma (47 papers, 2007 to 2025). The most malignant astrocytic tumor (WHO grade IV). "For example, brain overexposure to TGFβ2 as an anti-inflammatory approach might cause a malignant TGFβ2 autocrine loop that leads to glioblastoma." (PMID 32265815, 2020). "Schwartzbaum and colleagues investigated other growth factors from different pathways, with transforming growth factor-beta 2 (TGFB2) found to be inversely related to glioblastoma (OR=0.87, 95% CI=0.76-0.98) in the Janus Serum Bank (JSB)." (PMID 37265788, 2023). "Mechanistically, APOC1 drives the malignancy of glioblastoma by activating the TGFβ2 signaling pathway." (PMID 37981873, 2023). "While not fully characterized in colorectal cancer, inhibition of TGFβ3 in preclinical models of glioblastoma multiforme is associated with decreased expression of downstream SMAD oncogenes, decreased tumor invasiveness, and dampened TGFβ1/TGFβ2 signaling." (PMID 36382087, 2022). "TGFβ2 was originally isolated from a glioblastoma cell line as Glioblastoma-derived T-cell suppressor factor (G-TSF) and since then several cancers including melanoma, have been found to secrete increased amounts of this immunosuppressive cytokine." (PMID 35069536, 2021). "Among different isoforms, TGFβ2 is over-expressed in glioblastoma multiforme (GBM), melanoma, colon cancer, breast and prostate cancer." (PMID 30410671, 2018). "We found that TGFB2 is inversely related to glioblastoma (Odds Ratio (OR) = 0.87, 95% Confidence Interval (CI)) = 0.76, 0.98)." (PMID 26352148, 2015). "In conclusion, the miRNA-660-3p-APOC1 axis could inhibit the glioblastoma malignancy by negatively regulating the TGFβ2 signaling pathway." (PMID 37981873, 2023). "Further, we discovered that APOC1 inhibition downregulates TGFβ2 and disrupts its associated downstream SMAD3 and pSMAD3, revealing a new signaling pathway involving the miR-660-3p/APOC1/TGFβ2 axis in the development of glioblastoma." (PMID 37981873, 2023). "Our findings suggest that miR-660-3p/APOC1/TGFβ2 axis may serve as a new potential therapeutic target for glioblastoma." (PMID 37981873, 2023). "Our recent bioinformatics-led studies support the role of high levels of a specific TGF-β isoform, Transforming Growth Factor Beta 2 (TGFB2), and report that TGFB2 gene methylation serves as a significant prognostic marker in adult glioblastoma (GBM) and pancreatic adenocarcinoma (PDAC)." (PMID 41465326, 2025). "We previously reported that OT-101, a TGFB2-targeting S-ODN, exhibited promising single-agent clinical activity in adult patients with recurrent or refractory glioblastoma and anaplastic astrocytoma when administered intratumorally via CED." (PMID 36980562, 2023). "In contrast, IL1RL1, TGFB2, GLI1, and EDNRB was over-expressed in classical, and desmoplastic medulloblastoma, and glioblastoma." (PMID 31973134, 2020). "There are no previous data on CREB1 in CD, but it has been related to other diseases like human colorectal cancer, where CREB1 acts as a TF for tumor driver RRM2, or glioblastoma, where CREB1 acts as a mediator of the induction of TGFβ2." (PMID 29748492, 2018). "FAP expression correlated with TGFB1 and TGFB3, but not TGFB2 in all glioblastomas and in the mesenchymal subtype." (PMID 33494271, 2021). "Since in patient-derived in vivo models of glioblastoma, CREB1 levels have been found to determine the expression of TGFB2, CREB1 has been proposed a biomarker to stratify GBM patients for anti-TGF-β treatments and eventually as a therapeutic target in anti-TGF-β therapies." (PMID 33478130, 2021). "Data on the influence of TGFβ2 on APC are scarce, but this cytokine has been shown to inhibit the antigen presenting abilities of epidermal APC in mice, and its presence correlated with tumour progression, despite peripheral antitumour T-cell activity in glioblastoma patients." (PMID 17565341, 2007).
glioblastoma (continued). "High TGFB2 mRNA level was a poor prognostic indicator for DIPG patients but not for DMG patients whose tumors were outside of the pons/brainstem in locations such as the cerebellum and thalamus or pediatric glioblastoma (GBM) patients." (PMID 36980562, 2023). "TGFB2 may have a negative impact on survival in glioblastoma (GBM) patients, as suggested by increased survival duration at increased IL-1beta mRNA levels or low TGFB2 levels." (PMID 40338274, 2025). "Our study also demonstrated that RNA sequencing (RNAseq)-based high TGFB2 mRNA level is an indicator of poor prognosis for DIPG patients, but not for pediatric glioblastoma (GBM) patients or pediatric diffuse midline glioma (DMG) patients with tumor locations outside of the pons/brainstem." (PMID 36980562, 2023).
primary open-angle glaucoma (47 papers, 2011 to 2026). "Transforming growth factor β2 (TGFβ2), which is a risk factor for primary open angle glaucoma (POAG), increases expression of both αv and β3 integrin subunits." (PMID 35573686, 2022). "In recent years, an experimental mouse model of open-angle glaucoma was successfully created via intraocular injection of adenovirus-5 (Ad5) constructs carrying an active human-TGFβ2 (hTGFβ2) gene." (PMID 35805889, 2022). "These include transforming growth factor β2 (TGFβ2) in primary open angle glaucoma (POAG) and TGFβ1 and connective tissue growth factor (CTGF) in pseudoexfoliation glaucoma (PXFG)." (PMID 27124111, 2016). "In contrast, Yamamoto and colleagues reported that there was a decrease of total TGFβ2 in the aqueous humor, but it was still higher in open angle glaucoma (OAG) eyes compared to non-OAG eyes." (PMID 34499703, 2021).
melanoma (42 papers, 2007 to 2025). A malignant, usually aggressive tumor composed of atypical, neoplastic melanocytes. "They express transforming growth factor β receptor 1 (TGFβR1), and are therefore susceptible to TGFβ1 and TGFβ2 specifically expressed by primary melanoma." (PMID 17565341, 2007). "This study provides some evidence that variants in TGFB2 might also be associated with melanoma susceptibility." (PMID 22216283, 2011). "The protein products of TGFβ-2 and TGFβ-3 are expressed only by neoplastic cells and participate in melanoma progression." (PMID 36899279, 2023). "We further employed IHC on the matched mouse melanoma tissues to validate that TCF12 depletion decreased TGFB2 protein while TCF12 overexpression boosted TGFB2 levels." (PMID 37760480, 2023). "In summary, we identified that TCF12 can directly bind to the Tgfb2 promoter and activate its expression in melanoma." (PMID 37760480, 2023). "Together, we confirmed that TGFB2 was essential for TCF12 to induce melanoma proliferation, migration, and invasion." (PMID 37760480, 2023). "Our finding that TGFB2 is a direct transcriptional target of TCF12 suggests a mechanism by which TCF12 contributes to melanoma progression." (PMID 37760480, 2023). "The analysis of the melanoma patient serum cohort revealed for the first time a potential relationship between TGFβ2 and sCTLA-4 in melanoma patients and also raised the prospect that TGFβ2 has a role in stimulating the production of sCTLA-4." (PMID 35069536, 2021). "Serum levels of TGFβ1 were significantly raised in both the melanoma and lupus patient serum cohorts compared with healthy donors, but TGFβ2 serum levels were significantly higher solely in the melanoma patient cohort." (PMID 35069536, 2021). "Our study confirmed significantly higher serum levels of both TGFβ1 and TGFβ2 within the melanoma patient cohort, while analysis of lupus patient sera from a previous study identified high levels of TGFβ1 but little TGFβ2 compared with healthy donor sera." (PMID 35069536, 2021). "Further, we identified a mechanistic relationship where melanoma patient TGFβ2 serum levels correlated with sCTLA-4 levels and provided the basis for a novel protocol to enhance sCTLA-4 production and secretion by T cells with TGFβ2." (PMID 35069536, 2021). "The correlation of sCTLA-4 with TGFβ2 serum levels exclusively in melanoma patient sera was surprising and immediately raised the notion of a potential new mechanism of immune cell evasion." (PMID 35069536, 2021). "The secretion of TGFβ2 by melanoma cells was essential for their metastases to the brain parenchyma." (PMID 33115518, 2020). "TGFβ2 is an isoform of TGFβ in mammals and is abnormally expressed in various cancers, such as human melanoma and hepatocellular carcinoma." (PMID 33100909, 2020). "Patterns of TGFβ2 expression were sufficient to spatially distinguish brain metastases arising from the B16 and K-1735 murine melanoma cell lines." (PMID 30053879, 2018). "This supports the idea that levels of TGFβ2 play a pivotal role in the spatial distribution of BM, but the precise role of TGFβ signaling in this process has yet to be deciphered for human melanoma." (PMID 30053879, 2018). "To corroborate our result, we also compared basal values of PAX3d, MITF-m and TGFB2 obtained in recurrence-free patients to those observed six months before melanoma relapse in subjects with a disease progression." (PMID 29156734, 2017). "Given the critical functions of the TGF-β pathway in cancer biology, we speculated whether TGFB2 mediates the tumorigenic activity of TCF12 in melanoma." (PMID 37760480, 2023). "However, TGFB2 expression incrementally rises from initial to metastatic melanoma phases, suggesting its potential role in melanoma’s malignant evolution." (PMID 37760480, 2023).